ZNF423 (zinc finger protein 423)
Description:
Transcription factor that can both act as an activator or a repressor depending on the context. Plays a central role in BMP signaling and olfactory neurogenesis. Associates with SMADs in response to BMP2 leading to activate transcription of BMP target genes. Acts as a transcriptional repressor via its interaction with EBF1, a transcription factor involved in terminal olfactory receptor neurons differentiation; this interaction preventing EBF1 to bind DNA and activate olfactory-specific genes. Involved in olfactory neurogenesis by participating in a developmental switch that regulates the transition from differentiation to maturation in olfactory receptor neurons. Controls proliferation and differentiation of neural precursors in cerebellar vermis formation.
Synonyms: hOAZ; KIAA0760; NPHP14; OAZ; Ebfaz; Zfp104; JBTS19; Roaz; ZFP423
Tractability: PROTAC: ubiquitination databases record sites on it.
Gene: Protein-coding gene on chromosome 16 (49,487,524 to 49,857,919, reverse strand). Ensembl gene ENSG00000102935.
Subcellular location: Nucleus
Subcellular location (Human Protein Atlas): Nucleoplasm
Pathways (Reactome):
Developmental Biology: Transcriptional regulation of brown and beige adipocyte differentiation by EBF2
Gene Ontology:
Molecular function: protein binding; sequence-specific DNA binding; DNA-binding transcription factor activity, RNA polymerase II-specific; RNA polymerase II cis-regulatory region sequence-specific DNA binding
Biological process: negative regulation of DNA-templated transcription; positive regulation of DNA-templated transcription; protein localization to cilium; negative regulation of cold-induced thermogenesis; Notch signaling pathway; positive regulation of BMP signaling pathway; regulation of DNA-templated transcription; regulation of transcription by RNA polymerase II
Cellular component: nucleoplasm; nucleus
Genetic constraint (gnomAD): Loss-of-function variants: 12 observed, 99.19 expected, observed/expected ratio (o/e) 0.12, 90% interval 0.077 to 0.2. The upper end of that interval is the gene's LOEUF score, 0.2, which puts it in group 1 of 6, group 1 being the genes least tolerant of losing a copy. Missense variants: 1,316 observed, 1,816.9 expected, observed/expected ratio (o/e) 0.72, 90% interval 0.69 to 0.76. Synonymous variants: 749 observed, 739.39 expected, observed/expected ratio (o/e) 1.01, 90% interval 0.95 to 1.08.
Gene-disease validity (ClinGen):
ClinGen rates the evidence that ZNF423 causes each of these diseases.
ciliopathy (autosomal recessive): Moderate. A genetic disorder of the cellular cilia or the cilia anchoring structures, the basal bodies, or of ciliary function.
Homologues: Orthologues: pig ZNF423 (99% identical), chimpanzee ZNF423 (99% identical), guinea pig ZNF423 (99% identical), macaque ZNF423 (99% identical), mouse Zfp423 (98% identical), rabbit ZNF423 (98% identical), dog ZNF423 (97% identical), rat Zfp423 (97% identical), tropical clawed frog znf423 (87% identical), Caenorhabditis elegans ztf-16 (8% identical), zebrafish znf423 (7% identical), Caenorhabditis elegans sdz-12 (7% identical), and 2 more. Paralogues in human: ZNF521 (64% identical), ZNF462 (21% identical), ZNF445 (12% identical), ZNF786 (11% identical), ZNF211 (8% identical), ZBTB39 (8% identical), ZNF597 (6% identical).
Diseases named in the same sentence as ZNF423 in open-access papers:
ZNF423 is named in the same sentence as 47 diseases in open-access papers, as found by Europe PMC text mining. Sharing a sentence is not in itself a finding about the gene and the disease. The quoted sentences say what the papers report.
Obesity (16 papers, 2017 to 2025). Accumulation of substantial excess body fat. "The significant down-regulation of ZNF423 in umbilical cord blood may be related to the higher possibility of suffering obesity in offspring exposed to GDM." (PMID 35606885, 2022). "Mice with adipocytes that genetically lack zinc-finger protein 423 (ZFP423), a transcriptional repressor of EBF2 and thus the thermogenic gene program, exhibit increased adipocyte thermogenesis and CKB protein expression in subcutaneous fat, and protection from obesity during mistimed feeding." (PMID 37736043, 2023). "The gene product of ZNF423 promotes the transformation of non-adipocytes into adipocytes and inhibits subcutaneous adipogenesis, leading to adipocyte hypertrophy and inflammation, and finally developing to obesity and insulin resistance." (PMID 35606885, 2022).
neuroblastoma (12 papers, 2013 to 2023). Neuroblastoma (NB) is the most common solid, extracranial childhood tumor. "Analysis of conserved SDH-loss master regulators in human tumors and MEFs implicated ZNF423, a known modulator of retinoic acid response in neuroblastoma." (PMID 31234811, 2019). "This analysis of conserved SDH-loss MRs in human tumors and MEFs inferred ZNF423/ZFP423, a known modulator of retinoic acid response in neuroblastoma." (PMID 31234811, 2019). "Epigenetic loss or reduction of ZNF423 expression in human neuroblastoma corresponds with lower response to retinoic acid therapy and ectopic activation of Zfp423 in bone marrow cells induced B-cell leukemia in a mouse model." (PMID 23762491, 2013). "In addition, an association between inactivated NF1 and ZNF423 levels in neuroblastomas has been identified as a putative prognostic marker." (PMID 28637487, 2017). "Altered ZNF423 expression has been reported in different cancers, including breast cancer, ovary cancer, and neuroblastoma." (PMID 37658903, 2023). "Low expression of the transcription factor ZNF423 induces growth of tumor cells and correlates with a poor clinical outcome in neuroblastoma patients." (PMID 33596996, 2021). "ZNF423 has previously been described as a transcriptional cofactor of RARα/RXRα that is critically required for retinoic acid-induced differentiation of neuroblastoma." (PMID 31234811, 2019). "In neuroblastoma cells, being resistant to ATRA due to loss of the zinc finger protein ZNF423, the inhibition of the MAPK cascade restored ATRA responsiveness." (PMID 29131833, 2017). "In the case of neuroblastoma, ZNF423 displayed a clear trend of progressively decreased expression with more advanced tumour stages and lower expression was associated with worst prognosis." (PMID 26923714, 2016). "For instance, Zinc Finger Protein 423 was identified by a large-scale RNA interference screen to be critically required for RA-induced differentiation of neuroblastoma cells." (PMID 28066180, 2016). "We further examined ZNF423 expression among four neuroblastoma cell lines by quantitative RT-PCR (qRT-PCR)." (PMID 23762491, 2013). "Moreover, ZNF423 was previously reported to act as a co-activator of RARα/RXRα heterodimers in neuroblastoma cells." (PMID 31284679, 2019). "In neuroblastomas (NB), an RNA interference genetic screen identified ZNF423 as critical for retinoic acid-induced differentiation." (PMID 29867779, 2018). "Loss of NF1 activates RAS-MEK signalling, which in turn represses ZNF423, a critical transcriptional coactivator of the retinoic acid receptors; neuroblastomas with low levels of both NF1 and ZNF423 have an extremely poor outcome." (PMID 28637487, 2017). "Semi-quantitative RT-PCR from human cancer cell lines of neuroglial origin detected expression of ZNF423 and at least two of three EBF genes in both neuroblastoma (IMR32) and medulloblastoma (D238) derived cell lines." (PMID 23762491, 2013). "In a previous study the transcriptional co-activator ZNF423 was suppressed in neuroblastoma cells lacking NF1 due to overactive MAPK cascade signaling, finally leading to ATRA resistance." (PMID 29131833, 2017). "Additionally, we analyzed a transcriptional co-activator for retinoic acid receptors, ZNF423, which has been described to be lost in human NF1 lacking neuroblastoma cells." (PMID 29131833, 2017).
breast carcinoma (7 papers, 2017 to 2023). "As a result, our study has revealed a new potential biomarker signature involving CTSO and ZNF423-related SNPs for the therapeutic stratification of patients at high risk for the development of breast cancer." (PMID 28968398, 2017). "In the current study, based on our prior findings, we investigated the possible role of CTSO in drug response and breast cancer risk as a result of the regulation of ZNF423 and BRCA1." (PMID 28968398, 2017). "We previously performed a case–control genome-wide association study in women treated with selective estrogen receptor modulators (SERMs) for breast cancer prevention and identified single nucleotide polymorphisms (SNPs) in ZNF423 as potential biomarkers for response to SERM therapy." (PMID 28821270, 2017). "In highly proliferative breast cancer cells, estrogen was found to induce ZNF423 expression, a TF that has been confirmed to be upregulated in lipedema." (PMID 36551837, 2022). "We then selected a panel of breast cancer cells on the basis of ZNF423 SNP genotypes, specifically two cell lines containing the WT genotype and two containing the variant genotype to further confirm the SNP-dependent effect." (PMID 28821270, 2017). "Since our previous study had identified ZNF423 and CTSO SNPs that were associated with breast cancer risk, both of which appeared to regulate BRCA1, we examined their joint effect on cell proliferation in the presence of tamoxifen or E2 treatment." (PMID 28968398, 2017). "Our previous GWAS using samples from the NSABP P-1 and P-2 selective estrogen receptor modulator (SERM) breast cancer prevention trials identified SNPs in ZNF423 and near CTSO that were associated with breast cancer risk during SERM chemoprevention." (PMID 28856246, 2017). "Clustered, regularly interspaced short palindromic repeats (CRISPR)/Cas9 genome editing was applied to generate ZR75-1 breast cancer cells with different ZNF423 SNP genotypes." (PMID 28821270, 2017). "Knocking down ZNF423 or CALML3 altered the breast cancer cell response to several drugs including 4-OH-TAM, raloxifene, olaparib (PARP inhibitor) and cisplatin (platinum)." (PMID 28821270, 2017). "We used both LCLs from healthy subjects with known germline SNP genotypes as well as breast cancer cells with heterogeneous genetic backgrounds to provide insight into the effect of the ZNF423 SNP on gene transcriptional regulation." (PMID 28821270, 2017). "The combination of genotyping for CTSO SNPs and ZNF423 SNPs offers the potential for the stratification of ER+ breast cancer patients into different drug response subgroups." (PMID 28968398, 2017). "We previously reported a genome-wide association study that identified common SNPs near the CTSO gene and in ZNF423 associated with development of breast cancer during tamoxifen therapy in the NSABP P-1 and P-2 breast cancer prevention trials." (PMID 28968398, 2017). "This was consistent with our previous finding that the odds ratios for CTSO V/ZNF423 W (OR = 5.71) was the highest, and that for CTSO WT/ZNF423 V (OR = 1.00) was the lowest for breast cancer risk in the P-1, P-2 trials." (PMID 28968398, 2017). "Our initial GWAS had identified SNPs associated with decreased (ZNF423) and increased (CTSO) risk for breast cancer occurrence, both of which appeared to regulate BRCA1." (PMID 28968398, 2017). "Interestingly, the ZNF423 gene harbors four estrogen response element binding sites and its expression is induced by estradiol, as previously shown in breast cancer cells." (PMID 35625899, 2022). "Our results have demonstrated the mechanism by which the ZNF423 rs9940645 SNP might regulate gene expression and drug response as well as its potential role in achieving more highly individualized breast cancer therapy." (PMID 28821270, 2017). "Based on the observations we made in LCLs, we asked whether CALML3 might function as an ERα regulator, cooperating with ERα to regulate ZNF423 expression in ERα + breast cancer cells." (PMID 28821270, 2017).
breast carcinoma (continued). "Although ZNF423 functions as a DNA-binding transcription factor in several signaling pathways, its role in breast cancer and treatment response remains unknown." (PMID 28821270, 2017). "Furthermore, using CRISPR/Cas9-engineered ZR75-1 breast cancer cells with different ZNF423 SNP genotypes, striking differences in cellular responses to SERMs and PARP inhibitors, alone or in combination, were observed not only in cells but also in a mouse xenograft model." (PMID 28821270, 2017). "We genotyped the ZNF423 SNP and CTSO SNP in a panel of breast cancer cell lines and chose T47D, CAMA-1, and ZR75-1 cell lines carrying homozygous genotypes for ZNF423 and CTSO SNPs for further functional study." (PMID 28968398, 2017). "In the present study, we identified additional SNPs that might contribute to inherited variation in SERM breast cancer prevention therapy by deep sequencing across CTSO and ZNF423 and subsequent functional genomic studies." (PMID 28856246, 2017). "We then performed studies in ERα + breast cancer cells selected on the basis of ZNF423 SNP genotypes, and confirmed those results in clustered, regularly interspaced short palindromic repeats (CRISPR)-engineered ZR75-1 breast cancer cells with different ZNF423 SNP genotypes." (PMID 28821270, 2017). "We have demonstrated that a PARP inhibitor, which can effectively restore tamoxifen sensitivity in tamoxifen—resistant ER+ breast cancer cells, might be a potentially promising addition to tamoxifen as a combination regimen for patients carrying the CTSO V/ZNF423 W SNP genotype." (PMID 28968398, 2017). "Richard Weinshilboum from the Mayo Clinic in Rochester, Minnesota, USA, and colleagues previously showed that genetic variations in or near two genes—ZNF423 and CTSO—affected how well the drugs tamoxifen and raloxifene reduced the rate of breast cancer occurrence." (PMID 28856246, 2017). "In the estrogen-dependent BC cell lines ZR75-30 and ZR75-1, it was found that both ZNF423 and BRCA1 (Breast Cancer 1) could be induced by estradiol." (PMID 29867779, 2018).
ciliopathy (6 papers, 2013 to 2025). "ZNF423 mutations are associated with Joubert Syndrome, a ciliopathy causing cerebellar vermis hypoplasia and ataxia." (PMID 40541527, 2025). "Mutations in the human homolog ZNF423 have been reported in patients with ciliopathy diagnoses and anatomical findings reminiscent of Zfp423 mutant mice and a subset of patient mutations has been validated in mouse models." (PMID 32967895, 2020). "Mutations in mouse Zfp423 or its human ortholog ZNF423 are associated with a range of developmental abnormalities reminiscent of ciliopathies, including cerebellar vermis hypoplasia and other midline brain defects." (PMID 32967895, 2020). "Hildebrandt and co-workers identified mutations in human ZNF423 among patients with ciliopathy diagnoses." (PMID 27727273, 2016). "This raises the question of whether ZNF423 and Zfp423 mutations phenocopy ciliopathies by acting on downstream signaling events or represent bona fide ciliopathies by affecting cilium function upstream of signaling." (PMID 27727273, 2016). "Our work provides, in both mouse brain and human cell culture models, the first mechanistic connection between ZNF423/Zfp423 ciliopathy-related phenotypes and function of the primary cilium." (PMID 27727273, 2016). "Further, a recent study also showed that mutations in MRE11, ZNF423 and CEP164, genes which encode proteins that function within the DDR, can cause nephronophthisis, providing another link between DDR signalling and ciliopathies." (PMID 26908596, 2016).
Joubert syndrome (5 papers, 2015 to 2025). Joubert syndrome (JS) is characterized by congenital malformation of the brainstem and agenesis or hypoplasia of the cerebellar vermis leading to an abnormal respiratory pattern, nystagmus, hypotonia, ataxia, and delay in achieving motor milestones. "More recently, ZNF423/Zfp423, a gene implicated in rare cases of Joubert syndrome, was found to be required for the response to SHH, for DNA repair and CGP cell cycle progression." (PMID 33519389, 2020). "In Joubert syndrome with oculorenal anomalies, several mutations for ZNF423 have been identified including homozygous missense mutation of pP913L and heterozygous truncating mutations, pP506fsX43 and pH1277Y." (PMID 29867779, 2018). "Patients from all three ZNF423 families reported had cerebellar vermis hypoplasia or Joubert Syndrome, while two also had nephronophthisis and other clinical features." (PMID 27727273, 2016).
leukemia (4 papers, 2015 to 2018). A malignant (clonal) hematologic disorder, involving hematopoietic stem cells and characterized by the presence of primitive or atypical myeloid or lymphoid cells in the bone marrow and the blood. "The central enhancer CpGi at the human ZNF423 locus features >80% homology in mammals and, based on site-specific mutagenesis studies in leukaemia cells, has been shown to be relevant for the functional regulation of both α and β ZNF423 promoters." (PMID 29067487, 2018). "Methylation at multiple positions in these CpG islands affects the transcription in ES cells, and ALL leukemias bearing high ZNF423 expression display hypo-methylated CpG islands as compared to normal, lymphopoietic progenitors." (PMID 29867779, 2018). "However, as demonstrated in the leukaemia cells, methylation at the pre-adipocyte ZNF423 central enhancer island may also feature a repressive function as its presence closely correlated with reduced ZNF423 expression in the adipocyte precursor cells." (PMID 29067487, 2018). "In B-cell leukemias, aberrant ZNF423 induction increases EBF-binding and strongly blocks its action in determining B-cell differentiation, such that leukemia onset is favored and prognosis is poor." (PMID 29867779, 2018).